INSR (insulin receptor)
Diseases named in the same sentence as INSR in open-access papers (continued):
Sharing a sentence is not in itself a finding about the gene and the disease.
Insulin resistance (continued). "Most studies analysing these isoforms with regard to insulin resistance and T2DM have used skeletal muscle and adipose tissue with little data available on the relative expression of the INSR isoforms in the liver." (PMID 25742416, 2015). "To further confirm the role of myocardial insulin resistance in the development of ischemic HF, we used TCIRKO mice to achieve temporal control of insulin receptor disruption in the heart." (PMID 26659007, 2015). "The decrease in liver InsR and IRS expression is in accordance with the impairment of the hepatic insulin pathway and represents the therapeutic targets of insulin resistance." (PMID 25160038, 2014). "The peroxisome proliferator-activated receptor gamma (PPARG), Pro12Ala and the insulin receptor substrate (IRS1), Gly972Arg confer opposite effects on insulin resistance and type 2 diabetes mellitus (T2DM)." (PMID 24447396, 2014). "Akt is activated by the insulin receptor through PI3K, and aging is known to induce insulin resistance and decrease Akt phosphorylation in the liver of 24- to 28-month-old rats and 20-month-old mice." (PMID 24796965, 2014). "Reductions in the phosphorylated forms of insulin receptor (IR), insulin receptor substrate-1 (IRS-1), and expression of the Akt2 gene within adipose tissue and with time fasting are also suggestive of mounting insulin resistance in elephant seal weanlings." (PMID 24198811, 2013). "It has been shown that the lipid metabolism in patients with primary lipodystrophy, AKT2 mutations, or severe insulin resistance of unknown etiology have exaggerated forms of metabolic dyslipidemia and fatty liver in contrast to those with INSR mutations who did not." (PMID 23766565, 2013). "The altered levels of CUG-BP1 and MBNL1 result in reversion to embryonic splicing pattern of several mRNAs, such as the muscle chloride channel CLCN1 and insulin receptor INSR, resulting in myotonia and insulin resistance." (PMID 24705164, 2013). "As a novel identified negative regulator of insulin receptor signaling, DEP-1 represents a potential target for the treatment of insulin resistance and type 2 diabetes." (PMID 23889985, 2013). "Insulin resistance in type 2 diabetes can result in high phosphorylation of tau protein and the accumulation of Aβ peptide in brain indirectly via IDE or via insulin/insulin receptor signal pathway, leading to AD-like pathology and cognitive impairment." (PMID 24386004, 2013). "While no one mechanism of insulin resistance was clearly prevalent, significant changes were seen in two known pathways of insulin resistance, including increased JNK activity and reduced insulin receptor expression." (PMID 24252636, 2013). "HCV infection promotes insulin resistance, mainly through increased tumor necrosis factor α (TNF-α), which inhibit insulin receptor and IRS-1 (insulin receptor substrate) tyrosine phosphorylation." (PMID 22675572, 2012). "TNF-α rapidly induces insulin resistance by stimulating free fatty acid (FFA) synthesis and secretion, which interferes with post insulin receptor signaling via altered phosphorylation of insulin receptor substrates." (PMID 23056469, 2012). "In this respect it is to remind that proinflammatory cytokines can disturb insulin receptor and IGF-1 receptor signaling and that FFA induce insulin resistance." (PMID 22701480, 2012). "For example, in fat-specific insulin receptor knock-out mice (FIRKO), severe insulin resistance in adipocytes results in leanness and robust protection against obesity and glucose intolerance." (PMID 23024762, 2012). "Thus, regulation of InsR expression may improve insulin resistance in diabetes mellitus." (PMID 23213296, 2012). "The insulin receptor affinity and number in PCOS patients is equivalent to that of controls, insulin resistance is presumably mediated through downstream changes in the insulin receptor-mediated signal transduction cascade." (PMID 21209881, 2010).
Insulin resistance (continued). "All these cytokines can activate the insulin receptor substrate (IRS), exerting a negative effect on insulin signaling, which can cause insulin resistance." (PMID 39997751, 2025). "Considering that serine phosphorylation of the insulin receptor is one of the mechanisms of insulin resistance in PCOS, a unifying hypothesis was suggested for hyperandrogenism and insulin resistance, both of which are cardinal characteristics of PCOS." (PMID 40944006, 2025). "Elevated FFAs exacerbate insulin resistance by promoting lipid accumulation in non-adipose tissues like skeletal muscle and the liver, where they interfere with insulin receptor signaling." (PMID 41235339, 2025). "Insulin receptor plays a very important role in insulin signaling and thereafter energy metabolism, while insulin resistance is exhibited with no response to insulin stimuli." (PMID 41020854, 2025). "Furthermore, STAT3 inhibits the phosphorylation of insulin receptor substrates (IRS) by up-regulating SOCS3, exacerbates insulin resistance, and forms a vicious cycle of metabolism and inflammation." (PMID 41226680, 2025). "Dioscoreae Rhizoma exerts its effects primarily through its active metabolite Dioscorea polysaccharide (DPS); DPS ameliorates insulin resistance by increasing glucose absorption and GLUT2 expression while activating insulin receptor substrate phosphorylation and elevating p-Akt levels." (PMID 41585876, 2025). "The use of HI conditions stems from various studies indicating that elevated insulin levels could potentially play a role in fostering insulin resistance through dietary means, including HFD, and we check the levels of INSR in mouse primary hepatocytes." (PMID 39747658, 2025). "This suggests that post-receptor signaling abnormalities, independent of INSR splicing defects, are also a significant contributor to insulin resistance." (PMID 41018201, 2025). "This new mechanism of insulin resistance does not require the phosphorylation of traditional inflammatory mediators or insulin receptor substrates." (PMID 41425575, 2025). "Studies have shown that hyperglycemia in T2DM patients was found to induce mitochondrial fission and reduce mitochondrial fusion, and decreased MFN1/2 reduced insulin receptor substrate-AKT (IRS-AKT) signaling and Glucose Transporter 4 (Glut4) translocation, further increasing insulin resistance." (PMID 41195385, 2025). "Additionally, the JAK/STAT pathway, activated by IL-6, contributes to insulin resistance by inducing the expression of SOCS proteins, which inhibit insulin receptor signaling, impairing normal insulin function." (PMID 40004236, 2025). "Other work has shown a vital role for galectin-3 in regulation of insulin receptor responsiveness, and suggests that treatment with ARSB and enhanced binding of galectin-3 with less sulfated C4S may lessen insulin resistance." (PMID 37813168, 2024). "Insulin resistance, defined as reduced insulin sensitivity and detected in approximately 40% of patients with NAFLD, arises from the reduced expression of insulin receptors, ineffective insulin-receptor bindings, or impairment in insulin signaling." (PMID 38542310, 2024). "The development of fatty liver and hepatic insulin resistance, the activation of PKC-ε, and defects in insulin receptor signaling were all abrogated when rats fed a high-fat diet were treated with the mitochondrial uncoupler 2,4-dinitrophenol to increase energy expenditure." (PMID 39769002, 2024). "Despite well-recognized changes in insulin resistance with pregnancy, there was no change in insulin receptor (CD220) expression which is perhaps unsurprising given monocytes are insulin independent." (PMID 38736550, 2024).
Insulin resistance (continued). "The two protein molecules interacted with the insulin receptor, and their overexpression negatively regulated an insulin-induced phosphorylation of insulin receptor substrates (IRS, gene name: Irs1 and Irs2), which is one of the most important factors contributing to insulin resistance in the body." (PMID 39063287, 2024). "In addition, ceramides also aggravate brain insulin resistance by activating the phosphorylation of MAPK and JNK, hindering insulin binding to the insulin receptor IRS-1." (PMID 38379904, 2024). "Insulin receptor (IR) mutant mice display insulin resistance accompanied by hyperinsulinemia but do not show an extended lifespan compared to wild-type mice." (PMID 39451245, 2024). "The little available evidence in insulin-injected animals suggests that INSR activation may still be triggered in animal models of AD, even following HFD-induced insulin resistance, similar to the treatment of advanced T2DM." (PMID 37611907, 2024). "Furthermore, ER stress induces insulin receptor signaling through the increase in serine phosphorylation and a decrease in tyrosine phosphorylation of IRS-1, leading to insulin resistance." (PMID 38727305, 2024). "Although it is suggested that insulin resistance occurs due to the downregulation of the IR, or insulin receptor substrate (IRS) proteins, the precise mechanism of insulin resistance is unknown." (PMID 36831374, 2023). "The KYCCSRK peptide was shown to promote both the activation of the insulin receptor (IR) kinase activity and the activation of ERK1/2 and AKT downstream from IR on its own in HEK cells, thus representing a promising approach to counteract insulin resistance." (PMID 36670973, 2023). "Endoplasmic reticulum stress can also induce insulin resistance by activating the unfolded protein response (UPR), which can suppress insulin receptor expression or activate JNK or PERK, which can phosphorylate IRS-1 on serine residues and inhibit its tyrosine phosphorylation." (PMID 37680899, 2023). "INSR and TOX3 are significantly correlated to insulin resistance or metabolic syndrome." (PMID 36836035, 2023). "Mechanistically, an in vitro study reported that human insulin receptor can be cleaved by MMP8 and this observation could explain, at least partly, the role of MMP8 in impaired insulin signaling and insulin resistance in obese individuals." (PMID 37445827, 2023). "However, when insulin resistance is induced, the signaling of IRS-1, an insulin receptor substrate, and AKT, which regulates glucose and lipid metabolism, is downregulated, thereby affecting the expression of downstream factors." (PMID 37754257, 2023). "In addition, pro-inflammatory markers promote insulin resistance by reducing GLUT4 content, insulin receptor and IRS1 gene expression." (PMID 38027196, 2023). "Overactive mTOR and its resistance to insulin stimulation are considered pathological features of AD that represent insulin resistance independent of type-2 diabetes, along with impaired insulin receptor function in AD postmortem brain." (PMID 37457922, 2023). "We wanted to verify CNS insulin resistance, via CNS insulin receptor blockade using S961, did not affect distribution of 125I-insulin following IN delivery." (PMID 37076875, 2023). "Since the elevated FFA levels affect glucose metabolism by disrupting insulin receptor signaling in skeletal muscle and liver, elevated FFA levels by skipping breakfast may play an important role in developing insulin resistance." (PMID 36909337, 2023). "Compromised membrane fluidity can in turn aggravate impaired insulin resistance by inhibiting secretion of insulin- or GLUT-containing secretory granules, impaired insulin receptor signaling and increased membrane packing in the ER inducing ER stress leading to further saturated lipid synthesis." (PMID 37443733, 2023).
Insulin resistance (continued). "In a study examining the molecular basis of insulin resistance, researchers identified a small molecule, Co-Insulin, which binds specifically to insulin rather than to the insulin receptor (IR)." (PMID 38138975, 2023). "Furthermore, HFD-induced impairments were reversed by promoting insulin receptor substrates, while effects of insulin were abolished by inhibiting insulin receptor or PI3K34, implicating HFD-induced insulin resistance in impaired dopamine control." (PMID 34184629, 2022). "The trace element selenium, as a crucial part of antioxidative selenoproteins, can protect against the development of diet-induced insulin resistance in white adipose tissue (WAT) by increasing glutathione peroxidase 3 (GPx3) and insulin receptor (IR) expression." (PMID 35624726, 2022). "Thus, genes in the insulin signalling pathway, such as the insulin receptor (INSR), insulin receptor substrates 1 and 2 (IRS1 and IRS2), and GLUT4, are attractive candidates for insulin resistance." (PMID 35627115, 2022). "In addition, inflammatory signaling, mediated by cytokines or pattern recognition receptors, activate JNK and IKK kinases, which regulate insulin resistance by phosphorylating IRS, which prevents its activation by the insulin receptor." (PMID 35112705, 2022). "Collectively, our experiments suggest that hyperinsulinemia‐induced insulin resistance in muscle cells is mediated by a reduction in total INSR, and not primarily by affecting its activity or internalization." (PMID 34921686, 2022). "Interestingly, higher level of phosphorylated insulin receptor (p-Ser-IRS1) has been shown to be a consistent change in insulin signaling and a marker of insulin resistance in AD brains." (PMID 35264925, 2022). "Little evidence exists regarding the desensitization of the insulin receptor (IR); however, central insulin resistance has been shown to be related to cognitive and behavioral deficits." (PMID 35615716, 2022). "Lack of microglial InsR resulted in increased plasma insulin levels and insulin resistance in obese female mice." (PMID 35328354, 2022). "These kinases will mediate insulin resistance directly by downregulating insulin receptor expression, impair IRS-1 tyrosine phosphorylation, promote IRS-1 serine phosphorylation, leading to defective insulin receptor signaling." (PMID 35454131, 2022). "In addition, in adipose tissue, miR-155 promotes insulin resistance by downregulation of GLUT-4, decreasing the tyrosine phosphorylation of the insulin receptor and of IRS1, as well as attenuating the activation of Akt/PKB." (PMID 34440850, 2021). "According to our results, HRQoL did not display direct association with either of the ePRS-IRs, which suggests that the insulin receptor gene network does not affect HRQoL the same way insulin resistance does." (PMID 34732766, 2021). "Besides insulin receptor, GLP-1 receptor can also activate PI3K/Akt signalling pathway and improve insulin resistance." (PMID 34582711, 2021). "Recently, Gpx3 has been identified as a novel regulator of insulin receptor expression, and Gpx3 dysregulation would impact insulin receptor and lead to insulin resistance, a not uncommon feature in PAH patients." (PMID 34803695, 2021). "The novel variant Val1224Met showed normal expression of the mature INSR and INSR activity in CHO cells in vitro, which suggested this variant was not responsible for the severe insulin resistance." (PMID 33995269, 2021). "However, the insulin receptor expression in HFD+Ind mice was significantly higher than that in HFD mice and similar to that in STD animals, confirming that insulin resistance was prevented by indicaxanthin treatment." (PMID 35052584, 2021). "The increase in PI3K expression but not INSR expression suggests evidence of insulin resistance and/or an altered insulin signaling pathway in the hypothalamus of this group." (PMID 34248679, 2021).
Insulin resistance (continued). "Modulation of the insulin cascade at the proximal level involving the insulin receptor and IRS1/2 has gained considerable interest for explaining the pathophysiology of lipid-induced insulin resistance, pinpointing these mechanisms as key drivers of metabolic dysfunction in obesity and T2DM." (PMID 34440850, 2021). "Endothelial-specific mutant insulin receptor-overexpressing (ESMIRO) mice were generated to examine the contribution of endothelial cell insulin resistance on the vascular dysfunction and atherosclerosis as seen in whole body insulin resistance." (PMID 32401607, 2020). "However, human studies examining GLUT4 function have suggested that failed INSR signaling cascade activation and impaired GLUT4 translocation is the primary defect in skeletal muscle insulin resistance." (PMID 33038072, 2020). "Abdul-Ghani and DeFronzo described insulin receptor alterations, decreased PI3-kinase activation, impaired GLUT4 translocation and reduced glucose phosphorylation in the pathogenesis of skeletal muscle insulin resistance." (PMID 31968625, 2020). "Cytokines induce hepatic and peripheral insulin resistance in part via SOCS, which antagonize the insulin receptor mediated phosphorylation of IRS1/2 and can increase hepatic fat accumulation via antagonizing STAT3-mediated inhibition of the lipogenic transcription factor SREBP-1c." (PMID 32183037, 2020). "For example, severe insulin resistance was only observed in liver‐specific insulin receptor (IR) knockout mice and not in skeletal muscle‐ or fat‐specific IR knockout mice." (PMID 32936538, 2020). "The resulting “insulin resistance” is not primarily due to less insulin receptor expression on the cell surface but due to impaired insulin signal transduction as a result of receptor dysfunction." (PMID 32819363, 2020). "Furthermore, PSO upregulated obesity-mediated hepatic insulin receptor phosphorylation Tyr-972, p-IRB tyr1146, and pAMPK, thereby decreasing insulin resistance." (PMID 32751794, 2020). "Therefore, defects at the proximal level of insulin signaling that involve INSR, IRS1, PI3K, and Akt pathways are more evident in skeletal muscle insulin resistance, resulting in a decrease in insulin‐stimulated glucose uptake." (PMID 33038072, 2020). "Furthermore, it interferes with insulin receptor IRS-1 phosphorylation, leading to insulin resistance." (PMID 31824900, 2019). "This concept explains how GPCR-MMP9-IR crosstalk contributes to the development of insulin resistance through the over-activation of insulin receptor signaling without its ligand." (PMID 30884834, 2019). "Although other pathophysiological mechanisms could be involved in the development of insulin resistance in DM1, toxic aberrant mRNA resulting in dysregulated splicing of the insulin receptor mRNA is currently best supported in the literature." (PMID 31849810, 2019). "Cytokine-induced SOCS1 interacts with the phosphorylated insulin receptor, thereby preventing binding and activation of insulin receptor substrates (IRS), which leads to the inhibition of insulin signaling and the induction of insulin resistance." (PMID 31717271, 2019). "Another theory postulates that hepatic insulin resistance is mediated by other metabolic pathways independent of insulin-receptor signaling." (PMID 29534506, 2018). "To investigate whether the effect of peripheral insulin resistance observed in HFD is reflected in the brain, we measured the transcription level of insulin receptor in the hippocampus." (PMID 30079520, 2018). "Therefore, we evaluated the expressions of INSR, IRS1, PI3K, Akt, and GLUT4, the major proteins closely related to insulin resistance in the skeletal muscle." (PMID 29686718, 2018). "INSR-related severe insulin resistance compromises a phenotypical continuum, with the most severe phenotype seen in DS (leprechaunism) and a milder phenotype in RMS, with type A insulin resistance being a relatively mild form of SIR." (PMID 29695048, 2018).